HEATR5A (HEAT repeat containing 5A)
Synonyms: C14orf125; DKFZP434I1735; p200b
Tractability: PROTAC: ubiquitination databases record sites on it; its protein half-life has been measured.
Gene: Protein-coding gene on chromosome 14 (31,290,636 to 31,420,607, reverse strand). Ensembl gene ENSG00000129493.
Gene Ontology:
Biological process: endocytosis; intracellular protein localization; retrograde transport, endosome to Golgi
Cellular component: endocytic vesicle; Golgi apparatus; cytosol
Genetic constraint (gnomAD): Loss-of-function variants: 117 observed, 151.93 expected, observed/expected ratio (o/e) 0.77, 90% interval 0.66 to 0.9. The upper end of that interval is the gene's LOEUF score, 0.9, which puts it in group 3 of 6, group 1 being the genes least tolerant of losing a copy. Missense variants: 1,836 observed, 1,910.9 expected, observed/expected ratio (o/e) 0.96, 90% interval 0.92 to 1. Synonymous variants: 677 observed, 703.53 expected, observed/expected ratio (o/e) 0.96, 90% interval 0.9 to 1.02.
Homologues: Orthologues: chimpanzee HEATR5A (99% identical), macaque HEATR5A (98% identical), dog HEATR5A (90% identical), rabbit HEATR5A (89% identical), rat Heatr5a (88% identical), mouse Heatr5a (87% identical), guinea pig HEATR5A (83% identical), zebrafish heatr5a (63% identical), tropical clawed frog heatr5a (60% identical), Drosophila melanogaster CG2747 (47% identical), Caenorhabditis elegans soap-1 (36% identical). Paralogues in human: HEATR5B (59% identical).